PIM2 (Pim-2 proto-oncogene, serine/threonine kinase)
Description:
Proto-oncogene with serine/threonine kinase activity involved in cell survival and cell proliferation. Exerts its oncogenic activity through: the regulation of MYC transcriptional activity, the regulation of cell cycle progression, the regulation of cap-dependent protein translation and through survival signaling by phosphorylation of a pro-apoptotic protein, BAD. Phosphorylation of MYC leads to an increase of MYC protein stability and thereby an increase transcriptional activity. The stabilization of MYC exerted by PIM2 might explain partly the strong synergism between these 2 oncogenes in tumorigenesis. Regulates cap-dependent protein translation in a mammalian target of rapamycin complex 1 (mTORC1)-independent manner and in parallel to the PI3K-Akt pathway. Mediates survival signaling through phosphorylation of BAD, which induces release of the anti-apoptotic protein Bcl-X(L)/BCL2L1. Promotes cell survival in response to a variety of proliferative signals via positive regulation of the I-kappa-B kinase/NF-kappa-B cascade; this process requires phosphorylation of MAP3K8/COT. Promotes growth factor-independent proliferation by phosphorylation of cell cycle factors such as CDKN1A and CDKN1B. Involved in the positive regulation of chondrocyte survival and autophagy in the epiphyseal growth plate.
Tractability: Small molecule: a drug acting on it is in phase 1 trials; a structure with a bound ligand is known; a high-quality ligand is known; it has a high-quality binding pocket; it belongs to a druggable protein family. PROTAC: it is named in the literature on targeted protein degradation; ubiquitination databases record sites on it; a small molecule that binds it is known.
Target class: Kinase; Protein Kinase; CAMK protein kinase group; Enzyme; CAMK protein kinase PIM family
Chemical probes: LGH-447 (high quality)
Gene: Protein-coding gene on chromosome X (48,913,182 to 48,919,024, reverse strand). Ensembl gene ENSG00000102096.
Subcellular location (Human Protein Atlas): Cytosol
Gene Ontology:
Molecular function: protein binding; protein serine/threonine kinase activity; ATP binding; protein kinase activity; protein serine kinase activity
Biological process: G1/S transition of mitotic cell cycle; negative regulation of apoptotic process; negative regulation of cell population proliferation; protein stabilization; response to virus; positive regulation of autophagy; positive regulation of canonical NF-kappaB signal transduction; positive regulation of DNA-templated transcription; protein phosphorylation; regulation of mitotic cell cycle
Cellular component: cytoplasm
Homologues: Orthologues: chimpanzee PIM2 (99% identical), macaque PIM2 (99% identical), dog PIM2 (94% identical), guinea pig PIM2 (94% identical), pig PIM2 (93% identical), rat Pim2 (90% identical), mouse Pim2 (89% identical). Paralogues in human: PIM3 (59% identical), PIM1 (54% identical).
Diseases named in the same sentence as PIM2 in open-access papers:
PIM2 is named in the same sentence as 82 diseases in open-access papers, as found by Europe PMC text mining. Sharing a sentence is not in itself a finding about the gene and the disease. The quoted sentences say what the papers report.
myeloma (25 papers, 2014 to 2025). "Multiple myeloma has emerged as a promising area for PIM-inhibitor development associated with high activity of PIM2." (PMID 27556513, 2016). "To comprehensively elucidate the molecular mechanisms underlying enhanced DNA damage‐induced apoptosis in multiple myeloma (MM) cells through concurrent inhibition of PIM‐2 and PARP1, we performed RNA sequencing on U266 and RPMI‐8226 cell lines following combined treatment with SMI‐16a and ABT888." (PMID 40557764, 2025). "First, the precise mechanisms by which PIM‐2 inhibitors induce DNA damage in multiple myeloma (MM) cells remain undefined." (PMID 40557764, 2025). "The PIM‐2 inhibitor has emerged as a promising therapeutic approach for multiple myeloma, as highlighted by extensive reports and ongoing clinical studies supporting its potential efficacy." (PMID 40557764, 2025). "Although genome-wide surveys have detected NFKB1 rearrangements in myeloma (e.g. PIM2::NFKB1) and have exhaustively catalogued IGH translocation partners, an IGH::NFKB1 fusion has never been reported, supporting the novelty of the alteration described here." (PMID 41200196, 2025). "Pim‐1 is overexpressed in hematologic diseases and solid tumors, pim‐2 in myeloma, lymphoma, and leukemia, and pim‐3 in substantial organ tumors." (PMID 37162273, 2023). "Based on the current data, pim‐2 was expressed at a higher level in myeloma cells than pim‐1 and pim‐3, suggesting a more important role for pim‐2 in MM biology." (PMID 37162273, 2023). "In this study, we found that the level of Pim-2 increased in MM patients and was related to energy metabolism, which participated in the cell-cycle progression of myeloma cells, as indicated by mass spectrometry-based untargeted metabolomics analysis." (PMID 36612063, 2022). "Pim-2 kinase levels were significantly higher than those of other Pim family members in CD138+ myeloma cells in a series of 41 patients with newly diagnosed MM, suggesting that Pim-2 is relevant to MM cell proliferation." (PMID 36612063, 2022). "PIM2 modulated mTOR-C1 activity and promoted myeloma cell proliferation through phosphorylation of TSC2." (PMID 34503111, 2021). "The high expression of Proviral Insertion site for Moloney murine leukemia virus (PIM) kinases, especially PIM2, in myeloma cells is in agreement with the antiproliferative effect previously shown by the pan-PIM kinase inhibitor PIM447 in these types of cells." (PMID 32987735, 2020). "In multiple myeloma (MM), PIM2 expression in particular has been shown to be higher than in other hematologic malignancies." (PMID 32987735, 2020). "Pim-1 and Pim-2 are frequently overexpressed in hematological malignancies, such as AML, chronic myeloid leukemia, and multiple myeloma, and implicated in their pathogenesis through various mechanisms, including upregulation of the mTORC1 pathway." (PMID 29507660, 2018). "Myeloma shows common expression of PIM2 in particular, and early results announced at international meetings suggest promising clinical activity in heavily pretreated relapsed populations (see discussion)." (PMID 27556513, 2016). "This also implies a role for pim‐2 in the malignant proliferation of myeloma cells." (PMID 37162273, 2023). "Elevation of PIM2 reveals an anti-apoptotic function, which can be blocked by NF-κB inhibitor on multiple myeloma or lymphoma and PIM2 knockdown mice model of gastric cancer augmented apoptosis and diminished the proliferation of cells by high levels of ROS induced by PIM2 silence." (PMID 37223703, 2023). "PIM2 (proviral integration site for Moloney murine leukemia virus 2) kinase plays an important role as an oncogene in multiple cancers, such as leukemia, liver, lung, myeloma, prostate and breast cancers." (PMID 33854618, 2021). "For example, the expression of PIM2 in multiple myeloma cells could be regulated by IL-6 and TNF family cytokines, TNFα, BAFF, and APRIL." (PMID 32641749, 2020).
myeloma (continued). "A few studies showed that adipocytes could protect myeloma cells from chemotherapy induced apoptosis by increasing expression of Bcl-2 and Pim-2 protein." (PMID 27863383, 2016). "This study investigates how inducing DNA damage in multiple myeloma (MM) cells leads to MICA overexpression, facilitating NKG2D binding on NK cells.We analyzed the relationship between PIM‐2, PARP1, and MM prognosis using public data and clinical samples." (PMID 40557764, 2025). "Immunohistochemical analysis was carried out in vivo to investigate the effects of the combined PIM‐2 inhibitor SMI‐16a and PARP1 inhibitor ABT888 on multiple myeloma (MM)." (PMID 40557764, 2025). "PIM‐2 plays a pivotal role in DDR regulation, significantly influencing the survival and proliferation of multiple myeloma (MM) cells." (PMID 40557764, 2025). "Dependencies on POU2AF1 and PIM2, the target genes of TCF3 and IRF4 transcription factors, suggest cancer-type-specific addiction to transcriptional regulatory pathway in myeloma." (PMID 35382456, 2022). "SuperDendrix also finds associations for three downstream targets of TCF3 and IRF4 transcription factors: BCL2 and {leukemia, myeloma, MEF2B(A)}, PIM2 and myeloma, and POU2AF1 and Myeloma,MEF2BA." (PMID 35382456, 2022). "It is known that PIM2 modulates TSC2 phosphorylation and thus maintains multiple myeloma cell growth." (PMID 33931981, 2021). "For example, expression of both PIM1 and PIM2 is elevated in diffuse large B-cell lymphoma (DLBCL), whereas PIM2 alone is more highly expressed in B-cell chronic lymphocytic leukemia, acute myeloid leukemia (AML), and multiple myeloma (MM)." (PMID 29927999, 2018). "For example, PIM2 targets the TSC2 protein and enhances the mTOR‐C1 pathway to maintain cell growth in multiple myeloma, representing an important target in the treatment of tumor progression and bone loss in myeloma." (PMID 29570932, 2018). "Both PIM1 and PIM2 mRNAs are highly expressed in CLL, DLBCL and mantle cell lymphoma (MCL), whereas PIM2 is also overexpressed in follicular lymphoma, MALT lymphoma, nodal marginal zone lymphoma and multiple myeloma." (PMID 26643319, 2015). "PIM2 and PIM3 did not appear to be correlated with ABC protein expression, although these studies focused on leukemia and myeloma, in which PIM1 is known to play a larger role." (PMID 33727604, 2021).
lymphoma (22 papers, 2006 to 2023). A malignant (clonal) proliferation of B- lymphocytes or T- lymphocytes which involves the lymph nodes, bone marrow and/or extranodal sites. "The use of Pim-1 and Pim-2 expressing lymphoid cells in transgenic mice also causes a low frequency of lymphomas after long latency periods; whereas Pim-3 expressing liver cells of transgenic mice produce carcinomas but only in the presence of carcinogens." (PMID 36694243, 2023). "Latexin caused growth inhibition of lymphoma cells by significantly increasing apoptosis through the down-regulation of anti-apoptotic genes Bcl-2 and Pim-2." (PMID 23028717, 2012). "In humans PIM2 has been implicated in the transformation of both T and B lymphocytes and is highly expressed in human leukemia and lymphomas." (PMID 19841674, 2009). "Like Pim-1 the over-expression of Pim-2 in transgenic mice predisposes the mice to the development of lymphoma." (PMID 16403219, 2006). "Among them, high expression levels of PIM1 and PIM2 were more common in DLBCL, which were associated with active STAT signaling, lymphoma proliferative activity, and higher disease stage." (PMID 36871027, 2023). "In lymphoma cells, it has been suggested that PIM2 expression is induced by ATM activation after detection of DNA strand breaks." (PMID 38203596, 2023). "We found that lymphoma patients with high ETV6/PIM2 ratios (>1) had a worse outcome compared to patients with low ETV6/PIM2 ratios (<1; p = 0.01)." (PMID 35053500, 2022). "Transgenic mice overexpressing PIM1 or PIM2 were reported to develop lymphoma; therefore, these kinases have been regarded as oncogenic factors." (PMID 34503251, 2021). "PIM2 was identified in the 34 most highly overexpressed genes in MM cell lines compared to lymphoma and AML cell lines." (PMID 34503251, 2021). "SMI-4a has been reported to be a PIM2-specific kinase inhibitor that can block the growth of precursor T-cells in both leukemia and lymphoma." (PMID 34503111, 2021). "On the other hand, mouse #4 with MYC and PIM2 proto-oncogenes developed extensive lymphoma in various anatomical locations, and the cells clearly showed the phenotype of pro-B cell lymphomas as judged by CD43 and membrane IgM staining." (PMID 26606454, 2015). "The proviral insertion in murine (PIM) lymphoma proteins are a serine/threonine kinase family composed of three isoformes: Pim-1, Pim-2 and Pim-3." (PMID 25491234, 2014). "The inoculation of newborn BALB/c or C57BL1O mice with M-MuLV revealed insertions near the c-myc, pim1, or pim2 genes in the primary lymphomas." (PMID 24860787, 2014). "The administration of silvestrol, an inhibitor of eIF4E, was able to reverse pim2-mediated rapamycin resistance in human lymphoma cells and in vivo." (PMID 24860787, 2014). "Taken together, the data indicate that Pim-3 is the main Pim kinase overexpressed in Myc-induced lymphomas from mice and patients whereas Pim-1 and Pim-2 are more sporadically overexpressed." (PMID 21646687, 2011). "The oncogenic nature of Pim-1 and Pim-2 was confirmed by the observation that transgenic mice over expressing these kinases in the lymphoid system developed lymphomas." (PMID 22193779, 2011). "The serine/threonine kinase PIM2 is highly expressed in human leukemia and lymphomas and has been shown to positively regulate survival and proliferation of tumor cells." (PMID 19841674, 2009). "Over-expression of Pim-1 and Pim-2 in mice promotes the development of lymphomas, and up-regulation of Pim expression has been observed in several human cancers." (PMID 16403219, 2006). "A second related gene, Pim-2, was also identified as a common site of viral insertion in murine lymphomas." (PMID 16403219, 2006). "PIM2 is highly expressed in malignancies, such as lymphoma and multiple myeloma." (PMID 36871027, 2023). "Similar with previous report on lymphoma cells, TNFα treatment could upregulate the expression of PIM2 in a dose dependent manner on both QSG7703 and BEL7402 cells." (PMID 32641749, 2020).
lymphoma (continued). "Mouse #5 with MYC and PIM2 proto-oncogenes showed enlarged spleen and extensive lymphoma." (PMID 26606454, 2015). "The PIM2 gene is identified as a frequent site for retroviral insertion in experimental Lymphomas." (PMID 24505470, 2014). "The pim-1 proto-oncogene was first identified as a locus frequently activated by proviral integration in Moloney murine leukemia virus induced mouse T-cell lymphomas and pim-2 was identified as a gene frequently activated in secondary transplants of virus induced lymphomas." (PMID 22193779, 2011). "Therefore, when the animals were monitored for lymphomas, Eμ-myc/pim2- and Eμ-myc/AKT-expressing tumors had an accelerated disease onset compared to controls and histopathology and surface markers that were indistinguishable from those of aggressive pre-B-cell lymphomas." (PMID 24860787, 2014). "Previous studies have reported a high expression of PIM-1 and PIM-2 in ABC-DLBCL, which helps to distinguish it from germinal center B cell subtype lymphoma." (PMID 36871027, 2023). "This study confirmed that in lymphomas, the deletion of FOXN3 leads to increased level of the target gene PIM2, thereby weakening the inhibitory effect of FOXN3 on tumor growth." (PMID 31214487, 2019). "The PIM kinases (PIM1, PIM2, PIM3) are a family of serine/threonine kinases and were named for their mode of discovery as proviral common integration site in Moloney murine leukemia virus (mMuLV)-induced lymphomas." (PMID 34503111, 2021). "Hence, Pim2 and AKT activate protein translation and promote lymphomagenesis in a mouse model of aggressive and indolent lymphoma." (PMID 24860787, 2014). "Interestingly, both pim2- and AKT-expressing lymphomas relied on cap-dependent translation, and the rate-limiting factor for this translation is the activation of the cap-binding protein by phosphorylation of its inhibitor 4E-BP1, which can be further enhanced by direct eIF4E phosphorylation." (PMID 24860787, 2014).
breast cancer (20 papers, 2017 to 2026). A primary or metastatic malignant neoplasm involving the breast. "Pim2 deficiency in tumor antigen-specific or polyclonal T cells enhanced their ability to control tumor growth in murine breast cancer, melanoma, and leukemia models." (PMID 41592107, 2026). "PIM2 expression has been linked to the resistance of breast cancer and MM cell lines to PI3K inhibitors GDC-0941 or BKM12026,53." (PMID 35440108, 2022). "Recently, we found that PIM2 acts as an oncogene in breast cancer 15, 17, 22, but the underlying mechanism of its oncogene function remains largely unknown." (PMID 32754266, 2020). "Our findings provide new insights into the mechanisms underlying oncogenetic functions of PIM2 in breast cancer and may present new therapeutic strategies for breast cancer treatment." (PMID 29570932, 2018). "The combination of PFKFB3 and PIM2 has been reported to increase the glucose level in breast cancer cells (glucose detection kit, Sigma, GAGO20), so what role does PFKFB3 play in breast cancer patients with diabetes?" (PMID 36973739, 2023). "For other cancers, Pim-2 can promote glycolysis in some tumor cells by directly binding or changing the phosphorylation of PFKFB3 in breast cancer, PKM2 in HEK293T cells, and AMPKα in endometrial cancer." (PMID 36612063, 2022). "PIM2 is generally expressed in ovarian cancer, endometrial cancer, breast cancer, and other reproductive system tumors abnormally and at high levels." (PMID 36109523, 2022). "PIM2-regulated phosphorylation of HSF1 at Thr120 facilitated breast cancer oncogenesis in vivo and in vitro." (PMID 34239690, 2021). "PIM2, a serine/threonine kinase, has been shown to be highly expressed in many cancers, including breast cancer 22, liver cancer 28, stomach cancer 29, lymph cancer 30, ovarian cancer 31, endometrial cancer 16, prostate cancer 32, and lung cancer." (PMID 32754266, 2020). "To determine the mechanisms underlying PIM2 functions in breast cancer, we performed mass spectrometry analyses of the immunoprecipitated PIM2 complex in MCF-7 cells, and found that HK2 was associated with PIM2." (PMID 29985480, 2018). "But the mechanisms of PIM2 by which regulates breast cancer cell proliferation are still unclear, Our data showed that PIM2 was crucial in the regulation of TTP‐reduced proliferation and migration in breast cancer cells, consistent with previous studies." (PMID 29570932, 2018). "This conclusion was consistent with our experimental results that phosphorylation of HK2 by PIM2 enhanced glycolysis and contributed to the resistance of breast cancer cells to paclitaxel." (PMID 29985480, 2018). "Together, the results showed that phosphorylation of HK2 by PIM2 was important for breast cancer progression in vivo." (PMID 29985480, 2018). "This notion is clear given that 19% of PIM1 Tg female and a 7% of PIM2 Tg female harbored mammary tumors." (PMID 28938604, 2017). "Moreover, PIM2-mediated Thr473 phosphorylation of HKII promotes breast cancer cell glycolysis and autophagy under glucose starvation conditions." (PMID 37444501, 2023). "Furthermore, phosphorylation of HKII by PIM2 promotes glycolysis and autophagy, which confers breast cancer resistance to paclitaxel." (PMID 37444501, 2023). "We have previously demonstrated that PIM2 promoted glycolysis in breast cancer, however, it is unclear whether it can play a role in EM." (PMID 36109523, 2022). "PIM2 also interacts with tristetraprolin, thereby promoting breast cancer progression." (PMID 34511042, 2021). "To determine whether PIM2 regulates the effect of TTP on cell proliferation, we overexpressed HA‐tagged TTP and Flag‐tagged PIM2 in breast cancer cells." (PMID 29570932, 2018). "Indeed, PIM2 overexpression de‐repressed TTP‐mediated inhibition of breast cancer cell proliferation and migration in vitro and promoted breast tumor xenograft growth in vivo." (PMID 29570932, 2018).